LPIN2 (lipin 2)
Diseases named in the same sentence as LPIN2 in open-access papers (continued):
Sharing a sentence is not in itself a finding about the gene and the disease.
prostate adenocarcinoma (1 paper, 2021). "From the studies selected from cBioPortal, alterations in the LPIN1, LPIN2 and LPIN3 genes within prostate cancer, prostate adenocarcinoma, castration-resistant prostate cancer and prostate neuroendocrine carcinoma resulted in amplification being the major form of alteration." (PMID 33596934, 2021).
prostate carcinoma (1 paper, 2021). A carcinoma that arises from epithelial cells of the prostate gland. "Lipin-1, but not Lipin-2 or − 3, was detected in several prostate cancer cells, and was increased in 22RV1 and PC-3 cell lines." (PMID 33596934, 2021).
psoriasis (1 paper, 2012). An autoimmune condition characterized by red, well-delineated plaques with silvery scales that are usually on the extensor surfaces and scalp. "It has further been hypothesised that mutations in LPIN2 may play an etiologic role in psoriasis, since it localizes to a genomic region identified as a psoriasis susceptibility locus." (PMID 22685464, 2012).
SAPHO syndrome (1 paper, 2020). SAPHO syndrome (acronym for Synovitis, Acne, Pustulosis, Hyperostosis and Osteitis) is an auto-inflammatory disease, mainly characterized by the association of neutrophilic cutaneous involvement and chronic osteomyelitis. "Several other genes, such as PSTPIP2, NOD2, and LPIN2, have been found to be associated with SAPHO syndrome, although have yet to be confirmed pathogenic." (PMID 33153463, 2020).
infection (1 paper, 2023). The state of being infected such as from the introduction of a foreign agent such as serum, vaccine, antigenic substance or organism. "This also coincides with the changes in LPIN2 expression seen in cells from obese subjects post-infection." (PMID 37047702, 2023). "Having pointed out LPIN2 as a unique DEG in SARS-CoV-2-infected NHBE cells, the inflammatory profile was assessed during infection by qRT-PCR in an in vitro culture system." (PMID 37047702, 2023). "Interestingly, LPIN2 expression was retained in the infected NHBE cells from non-obese subjects after 24 h, to reach a maximal expression peak at 48 h post-infection, while those of obese subject group failed to overexpress LPIN2 after this timepoint." (PMID 37047702, 2023). "However, at 24 h post-infection, LPIN2 expression was decreased in the non-obese subject group and was rather increased in obese subject groups." (PMID 37047702, 2023).
tumor (1 paper, 2023). "Lipins may also affect tumor processes in glioblastoma by influencing peroxisome proliferator-activated receptors (PPARs) and, in the case of lipin 2, P2X7." (PMID 37046844, 2023).
LPIN2 also shares sentences with these, for which no sentence is quoted: Arthritis (2 papers); congenital dyserythropoietic anemia (2); abdominal aortic aneurysm (1); acne (1); breast carcinoma (1); cancer (1); coronary atherosclerosis (1); dyserythropoietic anemia (1); fatty liver (1); Hypercalcemia (1); Hypercholesterolemia (1); hypothyroidism (1); Immunodeficiency (1); Intellectual disability (1); metabolic disease (1); metabolic syndrome (1); microcytic anemia (1); neutropenia (1); prostate neuroendocrine carcinoma (1); pyogenic arthritis (1).